TNF (tumor necrosis factor)
Diseases named in the same sentence as TNF in open-access papers (continued):
Sharing a sentence is not in itself a finding about the gene and the disease.
respiratory infection (continued). "Six patients (30%) experienced side effects and five patients had mild recurrent upper respiratory infections, whereas one patient experienced severe CNS toxicity that could be related to treatment with TNF-alpha inhibitor." (PMID 24167521, 2013). "Since TNF is a crucial cytokine for defending against respiratory infections, understanding how it is regulated in the lung could help researchers to develop inhalable therapies to boost its production in patients with respiratory infections that are difficult to treat." (PMID 39620891, 2024). "Seropositive individuals had higher levels of CRP, TNF, and IL-6 in circulation 1–3 months post-symptom onset; but in samples from individuals 6–9 months post-symptom onset, levels were equivalent to those individuals who were seronegative and were recovered from other respiratory infections." (PMID 34835045, 2021). "Recent clinical studies have demonstrated that Bifidobacterium strains can elevate levels of IFN-γ, IL-2, tumor necrosis factor (TNF), serum IgA, and IgA-secreting cells during upper respiratory infections." (PMID 40083779, 2025). "Future prospective multicenter cohorts should enroll diverse COPD patients with acute lower respiratory infections across severity strata, employing standardized CRP assays alongside inflammatory mediators (IL-6, TNF-α)." (PMID 40630494, 2025). "Systemic inflammation, due to respiratory infection, is another contributing factor in the development of CFRD, through its mediators like interleukin (IL)-1 beta, IL-6, CXCL10, tumor necrosis factor (TNF)-alpha, and interferon (IFN)-gamma." (PMID 38541202, 2024). "Additionally, studies deciphered that both V. parvula and SARS-CoV-2 stimulate production of proinflammatory cytokines, mainly TNF-a, that might aggravate the inflammatory and pro-oxidative responses leading to diverse respiratory infection outcomes (74, –, 77)." (PMID 35579429, 2022). "In the acute phase, leptin is co-produced together with the main inflammatory interleukins (IL), IL-6, IL-1, and tumor necrosis factor-α (TNF-α), and acts on the sense of hunger and on the immune response, especially in respiratory infections." (PMID 32630032, 2020). "We first chose to focus our efforts on cytokines known to be essential for survival of primary murine LVS respiratory infection: IL-17A, IFN-γ, and TNF." (PMID 26379269, 2015). "The increased infection risk associated with anti-TNF therapy is also relevant in NPC1 patients, especially regarding respiratory infections, but there was no reported increase in infection rates." (PMID 35694196, 2022). "It has been determined that meloxicam has a stronger anti-inflammatory effect by reducing the synthesis of tumor necrosis factor (TNF)-alpha, a cytokine with proinflammatory effects, as well as inhibiting the cyclooxygenase (COX)-2 enzyme in respiratory infections." (PMID 34680771, 2021). "Respiratory infection with the attenuated Live Vaccine Strain (LVS) and the highly virulent SchuS4 strain of Ft engenders intense peribronchiolar and perivascular inflammation, but fails to elicit select pro-inflammatory mediators (e.g., TNF, IL-1β, IL-6, IL-12, and IFN-γ) within the first ∼72 h." (PMID 23554897, 2013).
allergic rhinitis (53 papers, 2008 to 2026). Inflammation of the nasal mucous membranes caused by an IgE-mediated response to external allergens. "In the prior study, proinflammatory cytokines, particularly TNF-α, were found to be essential for the production of antigen-specific IgE, and a deficiency in TNF-α prevented the emergence of allergic rhinitis." (PMID 38152266, 2023). "According to the cytokine profile in the preseasonal ASIT regimen, the development of allergic rhinitis was predominantly associated with IL-5 and IL-13 production, and bronchial asthma with IL-4, IL-5, IL-13, and TNF-α, which is consistent with other reports." (PMID 36439113, 2022). "Studies conducted on allergic rhinitis showed that there is an association of IL-4 with significant increase in IL-13 and TNF α." (PMID 20616938, 2010). "Our analysis suggests that the TNF signaling pathway and NF-kappa B signaling pathway may be the underlying therapeutic mechanisms of berberine in treating allergic rhinitis." (PMID 38796469, 2024). "Ultimately, the ameliorative effect of dictamnine on allergic rhinitis mice was confirmed through nasal symptom score, serum pharmacodynamic indices (immunoglobulin E (IgE), histamine, IL-2, IL-4, IL-6, and TNF-α), and histopathology." (PMID 40520177, 2025). "The molecular docking verification indicated that its ingredients bound well to the core targets of allergic rhinitis, and stigmasterol’s docking ability with TNF (−12.73 kcal/mol) is particularly prominent." (PMID 36897696, 2023). "In the co-seasonal ASIT regimen, only IL-9 (r=0.72-0.8, P<0.0001) and TNF-α (r=0.72-0.8, P=0.001 - P<0.0001) were significantly correlated with allergic rhinitis signs." (PMID 36439113, 2022). "Treatment of allergic rhinitis patients with kaempferol also reduced TNF-α, IL-6, IL-8, IL-1ß, and MIP-3α." (PMID 34552650, 2021). "The inhibitory effects of TQ on IL-4 production, OVA-specific IgE, TNF-α and IL-1b gene expression, edema, and eosinophil infiltration in the nasal mucosa were reported in a rat model of allergic rhinitis." (PMID 33859710, 2021). "The biological effectiveness was evaluated in rabbit models of ovalbumin-induced allergic rhinitis by measuring TNF-α, TGF-β and IL-1." (PMID 33501873, 2021). "A recent study using the iron chelator, di-2-pyridylketone-4,4-dimethyl-3-thiosemicarbazone, identified a dose-dependent reduction in serum levels of IL-1β and TNF-α in a murine model of allergic rhinitis." (PMID 32466384, 2020). "In experiments, TNF-α was required to produce antigen-specific IgE and to induce T-helper 2 cytokines and chemokines in allergic rhinitis." (PMID 33006996, 2020). "The nasal lavage fluid levels of MPO post-TNF-α challenge were increased in patients with allergic rhinitis." (PMID 27046957, 2016). "In contrast, low constitutive B1R expression is upregulated in human nasal epithelial cells in allergic rhinitis subjects compared to controls and in human primary bronchial epithelial cells post stimulation with IL-1β and TNF-α." (PMID 24475248, 2014). "Nasal lavage fluid levels of MPO recorded 24 hours post TNFα challenge were increased in healthy subjects (p = 0.0081) and in patients with allergic rhinitis (p = 0.0081) (c.f." (PMID 18234086, 2008). "Focusing on human nasal airways, patients suffering from allergic rhinitis have been shown to feature increased tissue expression of TNFα mRNA and increased nasal mucosal output of TNFα." (PMID 18234086, 2008). "Healthy subjects and patients with allergic rhinitis (examined out of season) were subjected to nasal challenge with TNFα (10 μg) in a sham-controlled and crossover design." (PMID 18234086, 2008). "Taken together, no marked differences emerged between healthy subjects and patients with allergic rhinitis regarding TNFα-induced effects." (PMID 18234086, 2008). "Nasal lavage fluid levels of MPO were increased 24 hours post TNFα administration in healthy subjects and in patients with allergic rhinitis (this study)." (PMID 18234086, 2008).
allergic rhinitis (continued). "Nasal lavage fluid levels of MPO recorded 24 hrs post TNFα challenge were increased in healthy subjects (p = 0.0081) and in patients with allergic rhinitis (p = 0.0081) (c.f." (PMID 18234086, 2008). "The present study, involving healthy subjects and patients with allergic rhinitis, demonstrates that intranasal TNFα produces a local inflammatory response." (PMID 18234086, 2008). "Further studies are warranted to examine effects of TNFα on eosinophil activities, tentatively involving patients with on-going allergic rhinitis." (PMID 18234086, 2008). "Supplementation with baicalin in the diet reduced the serum concentrations of IgE, IL-1β, IL-4, IL-6, TNF-α, and histamine in rats with allergic rhinitis, which suggests its potential as a therapeutic agent for allergic rhinitis through inhibition of inflammation mediators." (PMID 41463802, 2025). "Based on these findings, it may be deduced that stigmasterol treated allergic rhinitis by acting on TNF targets." (PMID 36897696, 2023). "This study aims to determine whether the combined blockade of IL-1β and TNF-α can alleviate the pathological allergic inflammatory reaction in the nasal mucosa and lung tissues in allergic rhinitis (AR) guinea pigs." (PMID 27046957, 2016). "However, the human nasal airway and allergic rhinitis can be used to monitor effects of TNFα (this study) and anti-TNFα drugs." (PMID 18234086, 2008). "Accordingly, and supported by observations on increased levels of TNFα in allergic rhinitis as well as common cold, TNFα may be a pro-inflammatory factor in inflammatory conditions of the nasal airway." (PMID 18234086, 2008). "Tentatively, further human in vivo studies may involve intervention with anti-TNFα measures in allergic rhinitis at seasonal allergen exposure." (PMID 18234086, 2008). "Additionally, the therapeutic impact of berberine on allergic rhinitis may occur by influencing inflammation-related pathways such as TNF and NF-kappa B signaling pathways." (PMID 38796469, 2024). "Accordingly, our overall conclusion is that TNFα administered to patients with allergic rhinitis out of season, when there may be some degree of nasal eosinophilia but not at all as marked as during season allergen exposure, does not produce any marked pro-eosinophil effects." (PMID 18234086, 2008). "It has been demonstrated in in vivo allergic rhinitis models that BBR treatment targets were primarily involved in pathways such as NFκB, IL-17, tumor necrosis factor, and inflammatory responses." (PMID 41294852, 2025). "Splenocytes isolated from the DP-induced allergic rhinitis mouse model exhibited significantly increased IL-4, IL-10, IFN-γ, and TNF-α levels after stimulation with DP." (PMID 39335479, 2024). "The biological study revealed enhanced downregulation of inflammatory parameters; TNF-α, TGF-β and IL-1 in rabbit models of ovalbumin-induced allergic rhinitis compared to corresponding emulsion formulation." (PMID 33501873, 2021). "The targets of 48 putative therapeutic components in the treatment of allergic rhinitis include IL6, TNF, CXCL8, ICAM1, ILA, MMP9, IL10, and IL1B." (PMID 31611923, 2019). "There was a higher production profile of TNF-α and TSLP in nasal secretion in the patients with perennial allergic rhinitis and additional high sensitization to SEs." (PMID 29109963, 2017). "However, further studies may be warranted in order to elucidate whether TNFα has a specific role in allergic airway conditions: such studies are warranted based on observations that patients with allergic rhinitis feature increased tissue expression of TNFα mRNA and TNFα protein." (PMID 18234086, 2008). "In our previous study, involving patients with allergic rhinitis examined out of season, we observed moderately increased lavage fluid levels of ECP 24 hours after nasal TNFα challenge." (PMID 18234086, 2008).
allergic rhinitis (continued). "Furthermore, berberine (50 or 100 mg/kg) suppressed TNF-α, IL-6, IL-1β, IL-17, and IgE levels in the OVA-induced allergic rhinitis group (p < 0.01)." (PMID 38796469, 2024). "Furthermore, the results showed that coptisine suppressed OVA-induced allergic rhinitis symptoms, such as nasal rubbing and OVA-specific IgE, and histamine, IL-4 and TNF-α levels in the serum of AR mice." (PMID 30469322, 2018). "The combined blockade of IL-1β and TNF-α by the intranasal instillation of 0.1% anti-IL-1β/TNF-α IgY could be a potential alternative strategy for preventing and treating allergic rhinitis." (PMID 27046957, 2016). "Studies have shown that NF-κB also regulates the expression of TNF-α gene, which is of particular significance because TNF-α has also been shown to be an important mediator in the induction and maintenance of inflammation in allergic rhinitis." (PMID 23472126, 2013). "The only difference in TNFα induced effects between the groups was that the nasal mucosal numbers of neutrophils were increased in healthy subjects following TNFα challenge but not in patients with allergic rhinitis." (PMID 18234086, 2008). "A similar use of anti-TNFα drugs in allergic rhinitis is in our opinion not likely, in part reflecting that existing treatment options are very good and in part inherited difficulties with current anti-TNFα approaches." (PMID 18234086, 2008). "α-Pinene, the main component of SO, decreased TNF-α, IL-1β, IL-6, intercellular adhesion molecule-1 (ICAM), and macrophage inflammatory protein-2 (MIP-2) levels, as well as eosinophil and mast cell infiltration in the nasal mucosa in an ovalbumin-sensitized allergic rhinitis mouse model." (PMID 35744988, 2022). "TNFα increased the numbers of subepithelial neutrophils in the study material as a whole (p = 0.0021): a subgroup analysis revealed that this change reflected a statistically significant increase in the healthy group (p = 0.0015), but not in the allergic rhinitis group (p = 0.204)." (PMID 18234086, 2008). "Furthermore, studies in allergic rhinitis may elucidate specific roles for TNFα in type-1 allergic inflammation, which may not be done in allergic asthma where type-1 features may be blurred by chronic inflammatory features." (PMID 18234086, 2008). "Healthy subjects and patients with allergic rhinitis (examined out of season) were included in order to get a preliminary estimation regarding whether or not these group of subjects differ with regard to TNFα-induced effects." (PMID 18234086, 2008).
Arrhythmia (53 papers, 2010 to 2026). Any cardiac rhythm other than the normal sinus rhythm. "In the IR state, enhanced adipocyte inflammation and activation of cytokines such as TNF-α and IL-6 can promote atrial fibrosis and tissue remodeling, increasing susceptibility to arrhythmia." (PMID 41584292, 2025). "The advent of gene editingtechnologies further expands the possibilities for treating cardiovasculardisease by directly altering inflammation-related genes, such as TNF-α,to reduce cardiac inflammation and arrhythmia risk." (PMID 40776948, 2025). "In mice, extreme exercise-induced atrial enlargement was accompanied by fibrosis, inflammation, tumor necrosis factor (TNF) α signalling activation, and increased arrhythmia susceptibility." (PMID 39018488, 2024). "In this context, TNF-α and IL-1β have been reported to boost susceptibility to arrhythmia in rat ventricular myocytes through increase of calcium leakage from the sarcoplasmic reticulum." (PMID 26977143, 2016). "TNF‐α has been implicated as a proinflammatory cytokine in the induction of calcium leakage from the sarcoplasmic reticulum, which leads to QTc prolongation and arrhythmia." (PMID 37016545, 2023). "In experimental studies, the TNF-alpha system – whose activity can be assessed by the plasma level of sTNF-R1 – was found to influence calcium and potassium channels affecting QT time (shortening for the former and prolongation for the latter) and the susceptibility to arrhythmia." (PMID 24770373, 2014). "Cytokines like IL-6, TNF-α, and CRP disrupt cardiac function, increase oxidative stress, and promote fibrosis, heightening arrhythmia risk." (PMID 40281050, 2025). "In patients with AF, infiltration of inflammatory cells and elevated serum levels of mediators such as tumor necrosis factor-α (TNF-α), IL-1β, IL-6, IL-8, and IL-10 have been observed, correlating with the duration and severity of the arrhythmia." (PMID 41462903, 2025). "As inflammatory cytokines like TNF-α and IL-6 promote the generation of ROS, therapeutic strategies aimed at reducing oxidative stress hold potential in preventing arrhythmias." (PMID 40901119, 2025). "The use of cytokine inhibitors, such as IL-1 receptor antagonists, TNF-α blockers, and IL-6 inhibitors, has shown potential in other inflammatory diseases, and their application in arrhythmia management is under investigation." (PMID 40901119, 2025). "TNF-α and IL-1β arepotent pro-inflammatory cytokines that alter the electrical activity of atrialmyocytes, leading to arrhythmias." (PMID 40776948, 2025). "In several case-controlled studies, increased levels of inflammatory markers, such as CRP, IL-6, IL-8, and TNF, and elevated neutrophil and lymphocyte ratios have been reported in patients with arrhythmia compared with those in patients with sinus rhythm." (PMID 33796569, 2021). "In line with our results, elevated levels of the inflammatory cytokines TNFα and IL-1β have been reported in both tissue and plasma from HF patients with arrhythmias." (PMID 29962957, 2018). "Clinic studies have observed that pro-inflammatory factors such as tumor necrosis factor α (TNF-α), Interleukin 1 (IL-1) family members and monocyte chemo attractant protein 1 (MCP-1) were associated with arrhythmia." (PMID 26728597, 2016). "Arrhythmia has been reported as a side effect of treatment of patients with metastatic cancer with TNF-α, IL-2, and IFN-γ." (PMID 26284064, 2015). "As such, it may be prudent to monitor patients with known conduction disorders or prior arrhythmias more closely during and after administration of anti-TNF agents." (PMID 41010679, 2025). "Third, anti-TNF biologics show cardiac neutrality, exhibiting no significant increase in arrhythmia risk compared to unexposed controls." (PMID 41552252, 2025).